FLT3 (fms related receptor tyrosine kinase 3)
Diseases named in the same sentence as FLT3 in open-access papers (continued):
Sharing a sentence is not in itself a finding about the gene and the disease.
leukemia (continued). "We show that FLT3 inhibitors ranging from promiscuous to highly targeted are potent inhibitors of growth of leukaemia cells expressing mutant CBL in vitro, and we demonstrate in vivo efficacy of midostaurin using mouse models of mutant CBL." (PMID 31943762, 2020). "Recently, it has been shown that circMYBL2, a circRNA generated from the circularization of the cell-cycle checkpoint gene MYBL2, is crucial for FLT3-dependent leukemia progression." (PMID 32528957, 2020). "Mutations in the receptor tyrosine kinase genes KIT and FLT3 and the proto-oncogenes NRAS and KRAS have been observed in up to 80% of CBF leukemia patients and probably serve as cooperating factors during leukemogenesis promoting proliferation." (PMID 31896782, 2020). "Using a CFU assay, we also determined the effects of TP-0903 on the proliferation and differentiation of an FLT3-ITD mutant primary leukemia sample." (PMID 33268594, 2020). "When these cell lines were treated with 7.0 μM CPZ for 72 h, CPZ drastically (more than 90%) inhibited the growth and survival of MV4-11 and HMC-1 but showed only marginal (0–40%) inhibitory effects on leukemia cell lines with FLT3 WT/KIT WT." (PMID 32811837, 2020). "FLT3/ITD is extensively present in leukemia stem cells (LSCs) and is proposed to be a primary event in leukemogenesis in possessing CD123 (IL-3RA) stage, and is the main cause of poor prognosis in patients." (PMID 32641978, 2020). "On one hand it has confirmed the on-target effect of FLT3 inhibitors and their anti-leukaemia efficacy, on the other hand it contributes to drug-resistant leukaemia relapse." (PMID 32102366, 2020). "The extent of MRT 68921- or SBI-0206965-induced apoptosis was significantly higher in the primary FLT3-ITD blasts than in the leukemia cells obtained from FLT3-WT AML cases (MRT 68921; p = 0.0001, SBI-0206965; p < 0.0001)." (PMID 32393312, 2020). "Here, we show that targeted SYK inhibition similarly enhances the effects of midostaurin and other FLT3 inhibitors against mutant CBL‐positive leukaemia." (PMID 31943762, 2020). "A Phase 1b study of venetoclax and gilteritinib in patients with Relapsed/Refractory AML also demonstrated efficacy, with 50% of FLT3-mutant patients achieving composite complete remission and an additional 40% reaching a morphologic leukemia-free state." (PMID 32545904, 2020). "The impact of these ADCs, small molecule inhibitors, and FLT3 inhibitors on improving survival in children with leukemia and other cancers remains to be seen as pediatric clinical trials become increasingly available." (PMID 32050659, 2020). "Since FLT3 inhibitor therapy has been reported to induce terminal differentiation of leukemia cells, we determined the effects of TP-0903 on AML cell differentiation." (PMID 33268594, 2020). "The co-occurrence of mutations in DNMT3A, NPM1 and FLT3-ITD is the most frequent combination of mutations found in AML, which highlights the synergy of this complex gene interaction in causing leukemia." (PMID 32545659, 2020). "Pharmacological inhibition of STAT5 also blocks FLT3-ITD-driven leukemias in mouse xenograft models." (PMID 31963765, 2020). "The mutant-to-wild-type allelic ratio and the presence of concomitant nucleophosmin (NPM1) mutations influence the prognosis of this subset of patients defining different subclasses of FLT3 and/or NPM1-mutated leukemias." (PMID 32033196, 2020). "There were 8/13 (62%) post-transplant leukemia relapses in patients who were FLT3 MRD(+)/MRD-FC(+), 2/8 (25%) relapses in FLT3 MRD(−)/MRD-FC (+,) group and 1/7 (14%) disease recurrence in those who had FLT3 MRD(+)/MRD-FC(−)." (PMID 32333156, 2020). "Despite the availability of effective FLT3 inhibitors in the treatment of FLT3-ITD AML, leukaemia relapse remains to be a major cause of treatment failure." (PMID 32102366, 2020). "RS4‐11 and MV4‐11 cells are human leukaemia cell lines expressing endogenously similar levels of FLT3 WT or FLT3 ITD, respectively." (PMID 32155324, 2020).
leukemia (continued). "Cabozantinib (XL184) targets VEGFR2, c-MET, KIT (also known as CD117), AXL, and FLT3; and induces apoptosis in FLT3-ITD+ leukemia cells in a dose-dependent manner." (PMID 31694201, 2019). "Small-molecule tyrosine kinase inhibitors (TKI) against FLT3/ITD-driven leukemia, including sorafenib, have shown clinical efficacy on AML." (PMID 30947742, 2019). "Our recent study demonstrated that FLT3/ITD-positive leukemia cells resistant to tyrosine kinase inhibitors possess fundamental metabolic alterations characterized by mitochondrial dysfunction and upregulation of glycolysis." (PMID 30947742, 2019). "We have previously demonstrated the functional cooperation of Myb and C/EBPα in the regulation of the Flt3 gene in both haematopoietic and leukaemia stem cells." (PMID 30877232, 2019). "Third, the inhibition of glycolysis and GSH shall be further tested in vivo to investigate alternative therapeutic agents for leukemia resistant to FLT3 inhibitors." (PMID 30947742, 2019). "Unlike other antigens commonly expressed in normal cells (such as CD33 and fms like tyrosine kinase 3 (FLT3)), WT1 is considered to be a leukemia-associated antigen." (PMID 31628525, 2019). "Rosnet and colleagues reported that three out of five ALL subjects with increased expression of FLT3 in leukemia blasts." (PMID 31565544, 2019). "Based on these data, FLT3-ITD facilitates the interaction between leukemia cells and the microenvironment by enhancing CXCL12/CXCR4 signaling." (PMID 31434952, 2019). "According to some studies, FLT3-ITD mutations enhance leukemia cell chemotaxis toward CXCL12, thus providing a drug resistance mechanism underlying the poor effect of FLT3-ITD antagonists." (PMID 31434952, 2019). "For instance, the expression levels of the tyrosine kinase FLT3 in leukemia cell lines is proportionally correlated with the sensitivity to the GA derivative 17-AAG." (PMID 30726209, 2019). "Specific cytotoxicity against FLT3+ leukemia cell lines and primary cell lines in vitro, as well as little off-tumor cytotoxicity on normal hematopoietic stem cells, was observed." (PMID 30736352, 2019). "A xenograft mouse model also showed a significantly prolonged survival in FLT3+ leukemia bearing mice after anti-FLT3L CAR T cells." (PMID 30736352, 2019). "STAT5 induces the expression of its target genes, such as, cyclin D1, c-myc and the protooncogene Pim-1, which mediates the proliferative and antiapoptotic behavior of leukemia cells via the FLT3-ITD signaling pathway." (PMID 31434952, 2019). "A comparison with six sorted pro-B/pre-B samples—the normal cells considered to be closest to ALL blasts—in the oligo(dT) RNA-seq dataset confirmed that CD44 and FLT3 were highly expressed in the hyperdiploid leukemias." (PMID 30944321, 2019). "Particularly, it was shown that these leukemias depends on glycolysis and glutamine supply for their energetic metabolism: FLT3-TKI treatment blocks glucose uptake and mostly glycolysis, rendering the cells dependent on glutamine metabolism." (PMID 30813354, 2019). "This study aimed to elucidate the alteration of metabolomic profile of leukemia cells resistant to the FLT3 inhibitor." (PMID 30947742, 2019). "It showed that FLT3L CAR-T cells were able to robustly kill FLT3+ leukemia cells in vitro and showed more potent cytotoxicity toward FLT3-ITD cells than FLT3 wild-type (WT) cells." (PMID 29716633, 2018). "We explored the feasibility of combining FLT3 TKIs with ATO in the treatment of FLT3/ITD+ leukemias." (PMID 30250637, 2018). "The specific cytotoxicity against FLT3+ leukemia cell lines, primary AML cells, and normal hematopoietic progenitor stem cells (HPSCs) in vitro were evaluated." (PMID 29716633, 2018). "Our findings therefore highlight the potential benefit of targeting these leukaemias with clinical FLT3 inhibitors." (PMID 30596405, 2018).
leukemia (continued). "In conclusion, these results suggest that ATO is a potential candidate to study in clinical trials in combination with FLT3 TKIs to improve the treatment of FLT3/ITD+ leukemia." (PMID 30250637, 2018). "Recently, several studies have reported the synergistic effects of ATO and FLT3 TKIs on FLT3 mutant leukemia cells." (PMID 30250637, 2018). "After being co-cultured for 5 h, the higher expressions of CD107a were observed in FLT3L CAR-T cells co-cultured with FLT3+ leukemia cells." (PMID 29716633, 2018). "Several BET inhibitors are in development and have been shown to have activity across various subtypes of AML in mouse models including MLL-fusion leukemias, as well as leukemias bearing mutations in NPM1, Flt3-ITD and DNMT3A." (PMID 29545928, 2018). "Given that compromised DNA damage response and weakened cell cycle checkpoint promote the progression of AML, our data points to the potential role of Myc and Miz-1 in regulating these pathways in Flt3-ITD leukemia." (PMID 30420889, 2018). "It has been reported that FLT3-ITD is associated with high white blood cell counts and high leukemia cells counts in APL, suggesting that it closely relates to APL cell proliferation." (PMID 30289902, 2018). "We did additional experiments using BM MNCs from FLT3-ITD–induced leukemia in FOXM1-overexpressing and control transgenic mice." (PMID 30089730, 2018). "Significant increases in apoptosis and decreases in cell viability were also noted in FLT3/ITD+ leukemia samples in response to combination treatment whereas little change was observed in FLT3/WT leukemic and the normal BM MNC samples." (PMID 30250637, 2018). "For this goal, we described a new type of CAR-T cell directed to FLT3 using its ligand as recognizing domain, the FLT3L CAR-T cell, and demonstrated that it had potent but diverse antitumor activity to FLT3-WT and FLT3-ITD leukemia cells." (PMID 29716633, 2018). "Another interesting compound, sorafenib, was originally developed as an inhibitor of the serine/threonine kinase Raf but leukaemia clinical trials and physicians have capitalized on its off‐target inhibition of FLT3." (PMID 29327808, 2018). "The combination of ATO and FLT3 TKI resulted in potent inhibition on downstream targets of FLT3 signaling in FLT3/ITD+ leukemia samples, as was seen previously for the FLT3/ITD+ cell lines." (PMID 30250637, 2018). "Our data extend these findings in FLT3–TKD-mutated cells; we now demonstrate that CDK6 inhibition is also capable of inducing leukemia cell death in this setting." (PMID 30544932, 2018). "We have also shown chemosensitization using FLT3-ITD leukemia developed in a transgenic FOXM1-overexpressing model." (PMID 30089730, 2018). "We focused our efforts on FLT3ITD, FLT3N676K, and NRASG12D, as FLT3 and NRAS are the most common targets of mutations that deregulate signal transduction in AML, and studied clonal evolution of leukemia cells carrying subclonal activating mutations over time." (PMID 29720585, 2018). "Recent strategies using targeted therapies (i.e., FLT3 tyrosine kinase inhibitors—TKIs), have thus far yielded modest responses and most relapsed/refractory patients will still die of their leukemia." (PMID 30262727, 2018). "Our current findings disclose that these genetically homogeneous leukemia cells, in terms of BCR/ABL, KIT or FLT3 mutations, are epigenetically heterogeneous and can be distinguished by overexpression of FTO and reduction of m6A methylation." (PMID 30297871, 2018). "BDT001 inhibited FL-induced FLT3 phosphorylation in leukemia-derived RS4–11 cells, also measured by trFRET (b for phosphorylation assay validation) with an IC50 of 18–24 μM that was almost unchanged with increasing FL concentrations." (PMID 29531216, 2018).
leukemia (continued). "Expression of mutant NRAS and FLT3 in the mouse leukemia cell line Ba/F3 resulted in elevated phosphorylated p-AKT and p-ERK1/2, as well as p-STAT5 for FLT3ITD." (PMID 29720585, 2018). "We found that a broad range of anti-leukaemic agents–notably MCL-1 inhibitors, DNA damaging agents and FLT3 inhibitors–sensitise leukaemia cells to BAD-BH3." (PMID 29298347, 2018). "The clinical importance of Flt3 signaling requires further investigations into the role of FL and its receptor in leukemia." (PMID 28538663, 2017). "We found that the NOX-A12 'Spiegelmer', an L-enantiomeric RNA oligonucleotide that inhibits SDF-1α, showed in vitro and in vivo activity against BCR-ABL- and FLT3-ITD-dependent leukemia cells." (PMID 29299123, 2017). "Considering that Sp1/NFkB is also involved in the regulation of receptor tyrosine signaling, we examined the changes of two receptor tyrosine kinases, KIT and FLT3, which play a pivotal role in leukemia pathogenesis." (PMID 28415607, 2017). "Because our studies and others demonstrated that Sp1/NFkB is also involved in the regulation of tyrosine kinase signaling, as a proof of concept, we examined the changes of KIT and FLT3, the key regulators of leukemia pathogenesis." (PMID 28415607, 2017). "FLT3 alterations are well documented in leukemia and therapeutic compounds are being developed to inhibit the activity of the constitutively active FLT3 receptors." (PMID 27906677, 2017). "Based on our previous findings on SOCS1 in FLT3-ITD mediated leukemia we asked how SOCS family members are regulated by BCR-ABL expressing cells." (PMID 28753604, 2017). "Here, we show the ability of NOX-A12 to block SDF-1-induced migration of BCR-ABL-positive leukemia cells, as well as FLT3-ITD-positive leukemia cells." (PMID 29299123, 2017). "Before evaluating the efficacy of creno to target FLT3-ITD LIC, we confirmed the FLT3-ITD-selective effects of creno in leukemia cell lines." (PMID 29312564, 2017). "A concomitant COG phase 1 study of sorafenib in children with relapsed/refractory solid tumors or leukemias also identified tolerable dosing in children and reported complete responses in two of eight patients with FLT3–ITD AML, enabling subsequent HSCT." (PMID 29209600, 2017). "While this work was in progress, it was shown that Gadd45a plays a tumor suppressive role in other leukemias, such as FLT-3 and MLL-AF9 derived AML." (PMID 28086219, 2017). "Previous studies have examined acquisition of FLT3 mutation in serial samples during disease transformation, showing a higher frequency of FLT3-ITD during leukemia transformation." (PMID 27023522, 2016). "FLT3 overexpression correlates with unfavorable prognosis in adult AML cases as well as in infant leukemias." (PMID 27391351, 2016). "It was also confirmed that FL impaired the anti-leukemia effects of FLT3 inhibitors on primary AML cells." (PMID 27331411, 2016). "The repression of Crtc1, Flt3 and Mycbp was also found in leukaemia BM cells of mice with AE9a or FLT3-ITD/NPM1c+-induced AML." (PMID 27116251, 2016). "More importantly, TALEN-mediated FLT3 haplo-insufficiency impaired leukemia cell proliferation capacity, and these potent inhibitory effects on K562 cell proliferation were retained in vivo." (PMID 26669855, 2015). "The incidences of LTLS in the traditional high risk groups were as follows: age >60 years 28.8%, primary AML 26.8%, secondary AML 25%; WBC >100x109/L 50%, LDH >2xULN 21.6%, CD34+ leukemias 16.3%, NPMI 27.2% and FLT3 gene mutation 33.3%." (PMID 25775138, 2015). "Flt3 overexpression has been identified as a recurring feature of multiple leukemias, and, as seen in infant ALL, has created a lot of interest for targeted therapy in AML." (PMID 26484338, 2015).
leukemia (continued). "Here, using a designed TALENs approach, we generated a panel of isogenic clones carrying a mono-allelic mutation of FLT3 in K562 and OCI-AML3 leukemia cells." (PMID 26669855, 2015). "Isogenic clones with mono-allelic disrupted FLT3 were compared to an isogenic wild-type control clone and parental leukemia cells for transcriptional expression, downstream FLT3 signaling and proliferation capacity." (PMID 26669855, 2015). "Before establishing isogenic clonal leukemia models, we assessed the basal expression level of FLT3 in a panel of working cell lines representing AML and CML myeloid blast crisis by Western blot." (PMID 26669855, 2015). "Among recurrent AML mutations, FLT3 ITD has been defined a driver mutation, which sustains the founding clone for progression to a frank leukemia." (PMID 26384303, 2015). "The present findings also highlight the therapeutic potential of TALENs for leukemia therapy by disrupting FLT3 signaling." (PMID 26669855, 2015). "In vivo, TG02 induces tumor regression after oral dosing on both daily and intermittent schedules in a murine model of FLT3-ITD leukemia (MV4-11) and prolongs survival in a disseminated AML model with wt FLT3 and JAK2 expressed in HL-60 AML cell lines." (PMID 25914884, 2015). "C/EBPα is often inactivated in various subtypes of leukemia by multiple mechanisms, including phosphorylation of serine 21 that inhibits its function and results in a differentiation block in FLT3-ITD leukemic blasts." (PMID 25914884, 2015). "The in vivo anti-leukemia activities of SKLB-677 were evaluated in the FLT3-ITD-dependent MV4-11 tumor xenograft model using AC220 as a positive control." (PMID 26497577, 2015). "In the leukemia patient application, we focused specifically on the activating internal tandem duplication (ITD) mutations in FLT3 (FLT3-ITD), which are detected in approximately 20% of AML patients associated with a poor prognosis." (PMID 26438695, 2015). "In the sub-set of the leukemia patients with known FLT3-ITD status, the TAS-based ranking distinguished the positive and negative cases (P=0.00017, Wilcoxon rank-sum test)." (PMID 26438695, 2015). "Limited preclinical evaluation of crenolanib incubated with primary leukemia specimens from children with TKI-resistant FLT3-ITD/FLT3 D835 AML demonstrated moderate in vitro anti-leukemic activity." (PMID 24672775, 2014). "In the first class, oncogenes (RUNX1, FLT3, LEF1) or tumor suppressors (RUNX1, CEBPA) implicated in leukemia were selected." (PMID 24786086, 2014). "In the meantime, resistance to FLT3-targeted therapy poses a significant challenge in the treatment of FLT3-activated leukemia patients." (PMID 25295230, 2014). "In fact, LOH for the Flt3-ITD mutation was a very early and almost universal event during leukaemia development in Npm1c/Flt3-ITD double heterozygous mice, suggesting that this type of mutation can be rapidly acquired and selected for." (PMID 25056697, 2014). "We review the discovery of targeting FLT3, discuss currently available FLT3 inhibitors in pediatric leukemia and results of clinical trials to date, and finally, consider the future promise and challenges of FLT3 inhibitor therapy." (PMID 25295230, 2014). "We then stained MLL-AF9 primary leukemia bone marrow with antibodies against Flt3, lineage markers (Lin), Sca1, Kit, CD24, CD34, and CD16/CD32, and analyzed the samples by FACS." (PMID 25517911, 2014). "The first use of FLT3 inhibitors in leukemia patients was a small phase 1/2 trial of lestaurtinib monotherapy in adult patients with heavily pretreated, refractory/relapsed AML." (PMID 25295230, 2014). "The combination of the HDAC inhibitor SAHA with BPR1J-340 exhibits strongly synergistic anti-leukemia effect in FLT3-ITD+ cells." (PMID 24416160, 2014). "This section will summarize the best-characterized FLT3 inhibitors in use in pediatric leukemia, and discuss some relevant adult clinical trial data." (PMID 25295230, 2014).